API5 (apoptosis inhibitor 5)
Description:
Antiapoptotic factor that may have a role in protein assembly. Negatively regulates ACIN1. By binding to ACIN1, it suppresses ACIN1 cleavage from CASP3 and ACIN1-mediated DNA fragmentation. Also known to efficiently suppress E2F1-induced apoptosis. Its depletion enhances the cytotoxic action of the chemotherapeutic drugs.
Synonyms: AAC-11; API5L1; AAC11
Tractability: PROTAC: ubiquitination databases record sites on it; its protein half-life has been measured.
Gene: Protein-coding gene on chromosome 11 (43,311,955 to 43,344,530, forward strand). Ensembl gene ENSG00000166181.
Subcellular location: Nucleus; Cytoplasm; Cytoplasm (Isoform 3)
Subcellular location (Human Protein Atlas): Nuclear speckles
Gene Ontology:
Molecular function: fibroblast growth factor binding; protein binding; RNA binding
Biological process: negative regulation of apoptotic process
Cellular component: membrane; nuclear speck; nucleus; cytoplasm; spliceosomal complex
Genetic constraint (gnomAD): Loss-of-function variants: 5 observed, 49.89 expected, observed/expected ratio (o/e) 0.1, 90% interval 0.051 to 0.21. The upper end of that interval is the gene's LOEUF score, 0.21, which puts it in group 1 of 6, group 1 being the genes least tolerant of losing a copy. Missense variants: 260 observed, 481.36 expected, observed/expected ratio (o/e) 0.54, 90% interval 0.49 to 0.6. Synonymous variants: 147 observed, 173.67 expected, observed/expected ratio (o/e) 0.85, 90% interval 0.74 to 0.97.
Homologues: Orthologues: chimpanzee API5 (100% identical), macaque API5 (100% identical), rabbit API5 (99% identical), rat Api5 (99% identical), pig API5 (95% identical), dog API5 (95% identical), guinea pig Api5 (94% identical), mouse Api5 (94% identical), zebrafish api5 (83% identical), tropical clawed frog api5 (78% identical), Drosophila melanogaster cass (47% identical).
Diseases named in the same sentence as API5 in open-access papers:
API5 is named in the same sentence as 37 diseases in open-access papers, as found by Europe PMC text mining. Sharing a sentence is not in itself a finding about the gene and the disease. The quoted sentences say what the papers report.
cervical carcinoma (8 papers, 2014 to 2024). A carcinoma arising from either the exocervical squamous epithelium or the endocervical glandular epithelium. "API5 overexpression was shown to be associated with tumor progression and poor prognosis in patients with cervical cancer." (PMID 32903271, 2020). "The abrogation of API5 protein expression in human cervical cancer cells has been implicated in tumor regression and sensitivity to chemotherapy." (PMID 29731959, 2018). "Our study also showed that API5 expression in cervical cancer was associated with poor overall and disease-free survival." (PMID 25070070, 2014). "Base on the fact that API5 is overexpressed, we examined the association between expression of API5 and pERK1/2 in cervical cancer or CIN specimens." (PMID 25070070, 2014). "API5 expression levels were positively associated with pERK1/2 in cervical cancer (P < 0.001) and high grade CIN (P = 0.031)." (PMID 25070070, 2014). "Therefore, further studies are needed to establish the relationship between API5 and the aggressiveness of cervical cancer cells, and to identify the exact causation of API5 overexpression in cervical cancer." (PMID 25070070, 2014). "However, we showed that API5 expression in cervical cancer specimens positively correlated with resistance to chemo-radiation therapy, implicating API5 overexpression as a strong risk factor for poor outcomes in cervical cancer." (PMID 25070070, 2014). "API5 expression is associated with pERK1/2 in a subset of cervical cancer patients and its expression predicts poor overall survival, supporting that API5 may be a promising novel target for therapeutic interventions." (PMID 25070070, 2014). "To determine whether API5 overexpression is linked to clinical features of cervical cancer, we performed immunohistochemistry in a cohort of cervical tissues from patients with CIN or invasive cervical cancer." (PMID 25070070, 2014). "API5 protein expression levels were found to significantly correlate with the prognosis of cervical cancer, as high level of API5 protein expression in cervical cancer lesions is closely associated with advanced tumor stage and grade, and shorter overall survival for the patients." (PMID 25070070, 2014). "Recently, the impact of API5 expression in tumor cell proliferation has been clinically demonstrated in the context of cervical cancer and breast cancer." (PMID 38275765, 2024). "API5 has been shown to be upregulated in various cancers, such as breast cancer, colorectal cancer, cervical cancer, NSCLC, or B-cell chronic lymphoid leukemia." (PMID 38275765, 2024). "By generating Kaplan–Meier plots, this group indicated that API5 expression is an important prognostic factor in human cervical cancer; high API5 expression reflected significantly shorter disease-free survival and overall survival times." (PMID 33299138, 2020). "We further analyzed the expression of API5 protein in cytoplasmic and nuclear fractions of the HeLa cells which have the highest expression of API5 among the cervical cancer cell lines examined by western blot analysis." (PMID 25070070, 2014). "Taken together, these results demonstrate that API5 expresses in cervical cancer cell lines and is primarily localized in nucleus." (PMID 25070070, 2014). "API5 and pERK1/2 immunohistochemical staining were performed on a cervical cancer tissue microarray consisting of 173 primary cervical cancers, 306 cervical intraepithelial neoplasias (CINs), and 429 matched normal tissues." (PMID 25070070, 2014). "The expression of human API5 was investigated in human cervical cancer cell lines using western blot analysis." (PMID 25070070, 2014). "It is reasonable to deduce that up-regulated API5 expression was more frequent in poorly differentiated carcinomas as API5 putative invasiveness has been reported in cervical cancer cell lines." (PMID 25070070, 2014). "Altogether, these data indicated that API5 expression serves as an important prognostic factor in human cervical cancer." (PMID 25070070, 2014).
cervical carcinoma (continued). "API5 expression gradually increased according to the phases of cervical cancer progression, from normal tissues through low and high grade CINs to cervical cancers (P < 0.001)." (PMID 25070070, 2014). "Subsequently, we observed that API5 protein is overexpressed in human cervical cancer tissue specimens." (PMID 25070070, 2014). "Here, we investigated API5 expression in cervical cancer, its clinical significance, and its relationship with phosphorylated extracellular signal-regulated kinase 1 and 2 (pERK1/2) in development and progression of cervical cancer." (PMID 25070070, 2014). "The putative oncogenic role of API5 was suggested by Kim and colleagues in cervical cancer cell lines." (PMID 25070070, 2014). "In line with this hypothesis, Cho and colleagues have shown that API5 expression levels gradually increased during the normal-to-tumor transition of cervical carcinoma." (PMID 38275765, 2024). "Aac11 overexpression could protect human cervical cancer cells from apoptosis, while higher levels of API5 were associated with poor survival of NSCLC patients." (PMID 37095445, 2023). "Furthermore, we uncovered the FGF2-NANOG molecular axis as a downstream component of API5 signaling that is conserved in cervical cancer patients." (PMID 28092370, 2017). "Furthermore, we uncovered the FGF2-NANOG molecular axis as a downstream component of API5 signaling that is conserved in cervical cancer patients, as well as an in vivo zebrafish model." (PMID 28092370, 2017). "Immunohistochemical staining showed that API5 expression increased during the normal to tumor transition of cervical carcinoma (P < 0.001), and this increased expression was significantly associated with tumor stage (P = 0.004), tumor grade (P < 0.001), and chemo-radiation response (P = 0.004)." (PMID 25070070, 2014). "API5 effects on cell growth were assessed in cervical cancer cell lines." (PMID 25070070, 2014). "In the current study, we observed increased protein expression of API5 in 34.2% (52/152 cases) of cervical cancers, and API5 expression level gradually increased during the transition from normal tissue to cervical carcinoma, suggesting an important role of API5 in cervical tumor progression." (PMID 25070070, 2014). "Overall, our study suggests that overexpression of API5 is a common features in cervical cancer and might represent a novel prognostic marker for the disease." (PMID 25070070, 2014). "They reported that API5 overexpression could promote cell growth and invasiveness of cervical cancer cell line CUMC-6." (PMID 25070070, 2014). "In addition, API5 expression positively correlated with disease severity in cervical neoplasias and negatively with overall survival of cervical cancer patients." (PMID 25070070, 2014). "Our results not only suggest the promising potential of API5 as a prognostic and survival marker, but also warrant further studies on a possible link between the biological function of API5 and the pathogenesis of cervical cancer." (PMID 25070070, 2014). "Thus, our study suggests the possibility that the effect of chemo-radiation can be compromised in cervical cancer patients with API5 overexpression, an observation that can have profound clinical implications." (PMID 25070070, 2014). "In addition, API5 expression positively correlated with cervical cancers resistance to chemo-radiation therapy." (PMID 25070070, 2014). "The TMA contains 173 cases of cervical cancer, however due to the complexity of sectioning, staining, as well as heterogeneity of the samples, only 152 and 150 samples could be interpreted for the API5 and pERK1/2, respectively." (PMID 25070070, 2014). "In this report, we aimed at investigating the clinical significance of API5 and its relationship with phosphorylated ERK1/2 (pERK1/2) in development and progression of cervical cancer." (PMID 25070070, 2014).
cervical carcinoma (continued). "Importantly, FGF2 expression was positively correlated with expression of API5 and NANOG in cervical cancer tissue, validating the biochemical pathway that we proposed." (PMID 28092370, 2017). "However, there is no clear evidence showing API5 role in tumor progression of cervical cancer." (PMID 25070070, 2014).
virus infection (5 papers, 2015 to 2024). "This groundbreaking discovery adds a new layer of complexity to our understanding of API5-Hsp20 axis, particularly in the context of apoptosis regulation during viral infections." (PMID 38143869, 2023). "The results showed that API5 was upregulated along with virus infection, silencing of API5 led to increased WSSV copy numbers and apoptotic rate of hemocytes, highlighting its significance in the immune response." (PMID 38143869, 2023). "In summary, our study represents a pioneering exploration of API5- Hsp20 axis in mud crabs, shedding light on their roles in the immune response against viral infections." (PMID 38143869, 2023). "The results showed that API5 could regulate apoptosis and virus infection by cooperating with Hsp20, which improves our knowledge of API5-Hsp20 axis in the antiviral innate immune response of marine crustaceans." (PMID 38143869, 2023). "Taken together, using Avibirnavirus IBDV as a model of a nonenveloped RNA virus, we revealed the fine-tuned regulation mechanism of the conversion between SUMOylation and deSUMOylation of API5 upon virus infection and provided new ideas for the design of anti-IBDV agents." (PMID 34372697, 2021). "Furthermore, API5 initially recognized for its role in inhibiting cell apoptosis upon growth factor deprivation, emerges as a significant component of the immune defense against viral infections." (PMID 38143869, 2023). "Additional examples were Apoptosis inhibitory protein 5 (API5), which binds RNA/mRNA, and is involved in programmed cell death regulation; and protein Argonaute 3 (AGO3), which binds nucleic acids, and provides RNA silencing and defense responses to viral infections." (PMID 35822794, 2021).
hepatocellular carcinoma (4 papers, 2016 to 2023). A malignant tumor that arises from hepatocytes. "API-5 was found to inhibit apoptosis of hepatoma cells through NF-κB pathway, and E2F1-dependent apoptotic pathway." (PMID 38143869, 2023).
breast carcinoma (3 papers, 2017 to 2024). "Survival analysis in KM plotter suggested that higher API5 expression is associated with poor breast cancer patient survival." (PMID 37095445, 2023). "Given that we show that high expression of Api5 in breast cancer patients is associated with shorter recurrence free survival, we investigated the relationship between ERα and Api5 at the molecular level." (PMID 28881748, 2017). "In ERα breast cancer patients, Api5 overexpression is associated with poor survival, and may be used as a predictive marker of breast cancer recurrence free survival." (PMID 28881748, 2017). "In-silico analysis revealed elevated levels of Api5 transcript in breast cancer patients which correlated with poor prognosis." (PMID 37095445, 2023). "Initially, we carried out in silico analyses using TCGA and GENT2 datasets to understand expression pattern of API5 in breast cancer patients followed by investigating the protein expression in Indian breast cancer patient samples." (PMID 37095445, 2023). "The plot shows Api5 transcript levels are up-regulated in breast cancer tissue samples when compared to normal breast tissues." (PMID 37095445, 2023). "We observed morphometric changes including an increase in size and cell number indicating the possibility of cellular transformation, thus suggesting a plausible role of Api5 in breast cancer." (PMID 37095445, 2023). "Api5 expression was in average 1.285 fold higher in breast cancer tissues compared to normal tissues (p = 2.78 × 10−8)." (PMID 28881748, 2017). "Api5, hypothetically promotes tumor growth and has a potential relationship with ERα in breast cancer." (PMID 28881748, 2017). "Altogether, this study demonstrates the role of Api-5 as key partner in ERα-induced breast cancer invasiveness and tumorigenesis." (PMID 28881748, 2017). "We compared Api5 expression level of 389 invasive breast carcinomas versus 61 normal breast cancer tissues in the TGCA breast dataset." (PMID 28881748, 2017). "These in-vitro results indicated that Api5 participate to the ability of anchorage-independent growth of breast cancer cells, which is a signature of tumors with metastatic potential." (PMID 28881748, 2017). "We next examined the relationship between Api5 expression and breast cancer using the online Kaplan-Meier plotter (kmplot.com)." (PMID 28881748, 2017). "OncomineTM meta-analysis revealed that Api5 is significantly overexpressed in breast cancer patients and the online Kaplan-Meier plotter analysis predicted a poor prognosis in ERα positive breast cancer patients." (PMID 28881748, 2017). "In this report, we demonstrated that Api5 is overexpressed in breast cancer and predicts poor prognosis." (PMID 28881748, 2017). "In this report, we demonstrated that Api5 played a potential oncogenic role in ERα positive breast cancer." (PMID 28881748, 2017). "To investigate the clinical relevance of Api5 in breast cancer patients we performed a meta-analysis of published gene expression data using the OncomineTM database (Compendia Bioscience, Ann Arbor, MI)." (PMID 28881748, 2017). "Taken together, these data indicated that up-regulation of Api5 confers significant poor clinical outcome to breast cancer patients, particularly in the ERα positive subpopulation." (PMID 28881748, 2017). "Moreover, a role for API5 in estrogen (E2)-induced proliferation has been identified in ERα positive breast cancer cell lines." (PMID 38275765, 2024). "The ability of Api5 to regulate multiple signalling pathways may be an advantage for developing novel breast cancer treatment strategies." (PMID 37095445, 2023). "Furthermore, immunohistochemical analyses on breast cancer tissue samples showed that tumour tissues showed significantly higher Api5 expression when compared to the adjacent normal or reduction mammoplasty tissues." (PMID 37095445, 2023). "Api5 expression levels were observed to be elevated in Tamoxifen-resistant breast carcinomas." (PMID 37095445, 2023).
breast carcinoma (continued). "Interestingly, reduced levels of Api5 resulted in decreased tumorigenic potential in the malignant breast cancer cell line, MCF10CA1a and impeded FGF2 signalling." (PMID 37095445, 2023). "Since overexpression of Api5 was leading to a transformed phenotype, we wanted to explore whether down-regulation of Api5 could alter the cancerous phenotype in pre-malignant and malignant breast cancer cells." (PMID 37095445, 2023). "Only one general study correlated Api5 overexpression and breast cancer." (PMID 28881748, 2017). "Api5 major function being anti-apoptotic, it is of interest to note that ERα is also related to anti-apoptotic functions as breast cancer adenocarcinomas not expressing ERα or PR are associated with a decrease of the apoptotic index." (PMID 28881748, 2017). "Besides, Api5 expression favors tumorigenicity and migration and is necessary for tumor growth in vivo in mice xenografted model of breast cancer cell line." (PMID 28881748, 2017). "Api5 could thus represent a predictive marker for the recurrence free survival of the ERα positive breast cancer patients." (PMID 28881748, 2017). "In this study, we found an over expression of Api5 in human breast cancer." (PMID 28881748, 2017). "Taken together, these results demonstrated that Api5 markedly influence breast cancer cell migration, suggesting that it might contribute to the metastatic process." (PMID 28881748, 2017). "Interestingly, Di Benedetto and her group reported Api5 inhibition to reduce angiogenesis and increase in apoptosis in xenograft models, thereby highlighting the potential use of Api5 as a therapeutic target in metastatic breast cancers that are resistant to chemotherapy." (PMID 37095445, 2023). "Thus, we decided to investigate Api5 function at the molecular level in the estrogen responsive breast cancer cell line MCF7 and more precisely the functionality of the Api5 LXXLL motif that could drive an interaction with ERα." (PMID 28881748, 2017). "The elevated c-MYC expression also mediates EMT in breast cancers, thus possibly explaining the partial-EMT observed in Api5 OE cells." (PMID 37095445, 2023). "Conversely, Api5 knock-down downregulated FGF2 signalling leading to reduced proliferation and diminished in vivo tumorigenic potential of the breast cancer cells." (PMID 37095445, 2023). "We based our present study on the observation that Api5 is overexpressed in breast cancer and correlated to a poor survival outcome of ERα positive breast cancer patients and on a previous study in which it appeared that the nuclear factor Api5 could be a cofactor of ERα." (PMID 28881748, 2017). "In addition, the proliferation of the MDA-MB-231 ERα negative breast cancer cell line was insensitive to Api5 depletion (shApi5 versus sh0)." (PMID 28881748, 2017).
glioblastoma (3 papers, 2019 to 2025). The most malignant astrocytic tumor (WHO grade IV). "Analysis of the Cancer Genome Atlas data showed lower miR-224 expression levels and higher expression levels of its target API5 in male glioblastoma multiforme patients were correlated with poorer survival." (PMID 31179240, 2019). "Furthermore, the study showed that the miR-197-3p/API5 axis triggers progression and radioresistance in glioblastoma." (PMID 41009512, 2025). "In line with this hypothesis, API5 has been shown to be upregulated by UV irradiation of primary liver cells, and an increased expression of API5 protects primary liver cells from UV-induced apoptosis and to increase glioblastoma cells to radioresistance." (PMID 38275765, 2024).